CD4 (CD4 molecule)
Diseases named in the same sentence as CD4 in open-access papers (continued):
Sharing a sentence is not in itself a finding about the gene and the disease.
cancer (continued). "In KRAS-mutant subgroups, cancer tissue with lower expression of SDPR was accompanied with less infiltration of γ T cells and resting mast cells but higher abundance of plasma cells, CD4+ memory activated T cells and M1 macrophages." (PMID 33435990, 2021). "TIMER analysis revealed that FTL expression and CD4+ T cells were positively correlated in 11/31 (35.5%) cancers, negatively correlated in 2/31 (6.5%), and was not correlated in 18/31 (58.1%)." (PMID 33864445, 2021). "Therefore, the determination of the proportions of CD3+, CD4+, and CD8+ cells is useful in the evaluation of monitoring patients with immune status affected by cancer." (PMID 34054956, 2021). "We noted that Step2 (cancer antigen presentation), Step4 (including CD4 T cell, dendritic cell, macrophage, T cell, TH17 cell, and Treg cell recruitment), and Step6 (recognition of cancer cell by T cell) displayed statistical differences in anticancer immunity between the two groups." (PMID 34630563, 2021). "This analysis suggests that the presence of a higher number of unique, non-self CD8- and CD4-neoepitopes contributes to cancer survival, and that prospectively defining these neoepitopes using Ancer is a novel prognostic or predictive biomarker." (PMID 33976291, 2021). "Similarly, both CD4+ and CD8+ T cell response has been reported in recent clinical studies following neoantigen-specific vaccination, across multiple cancer types." (PMID 34012451, 2021). "CD4+ T and CD8+ T cells has a pivotal role in cancer protective immunity." (PMID 34220957, 2021). "CD4+ and CD8+ T cell responses play a central role in the elimination of cancer cells." (PMID 33597971, 2021). "The density of CD4+ and CD4+ Foxp3-positive T-cells in brain metastases with radiation was statistically higher in the carcinoma and stromal areas compared with those without radiation (p = 0.0343, p = 0.0173)." (PMID 34647108, 2021). "The densities of CD4+Foxp3+ cells were positively correlated with OS in the carcinoma area of the brain metastases, but not in the stromal areas." (PMID 34647108, 2021). "In contrast, activation of NK cells showed weak correlation with CD8+ T cells or CD4+ T cells, indicating the non-overlapping regulation of different lymphocyte subsets during cancer–immune interaction." (PMID 32200422, 2020). "In addition, PTGIS expression was significantly correlated with infiltrating immune cells, including B cells, CD4+/CD8+ T cells, macrophages, neutrophils, and dendritic cells, in various types of cancers." (PMID 32463792, 2020). "Furthermore, multifunctional CD4+ CTLs, which have characteristics and functions similar to those of cytotoxic CD8+ T cells, play an important role in the fight against cancer." (PMID 33105813, 2020). "Moreover, two CT genes, TDRD6 and TTK, were positively correlated with a number of immune cells, especially the CD4+/CD8+ T cells, implying strong host immune reactions to these two cancer antigens." (PMID 32728493, 2020). "To conclude, our pilot study of BAL in the lung parenchyma opposite the cancer lung, showed changes of CD4 + T-lymphocytes, while CD8 + T-lymphocytes showed no significant changes." (PMID 33199774, 2020). "Further T cell subset analyses revealed that ILT4 expression was correlated with decreased CD8+T cell and increased Treg frequency in both cancer nest and stroma, but not with altered CD4+T cell frequency." (PMID 32368343, 2020). "Mortality rates after diagnosis of cancer were lower during 2006–2015 than 1996–2005: these declines were not explained by changes in CD4 count and viral load at cancer diagnosis." (PMID 32003460, 2020). "For example, resting memory CD4+ T cells, activated mast cells, monocytes, and M1 macrophages are more abundant in inflammatory stages, while CD8+ T cells, follicular helper T cells, and M0 macrophages are more abundant in cancer tissues." (PMID 33017516, 2020).
cancer (continued). "Importantly, CD4 T cells and MHC class II TCRs therefore have the potential to orchestrate broad and long-lasting immune responses that enable cancer control." (PMID 31915853, 2020). "With the progress of cancer, TANs produce negative effects on the CD4+ helper lymphocytes and natural killer cells, which also facilitate the angiogenesis pathways and other factors that favor tumors." (PMID 32831972, 2020). "However, the effect of anti-CD25 is not limited to Tregs, leading to a significant reduction of activated CD4+ and CD8+ effector cells generated during the immune response against cancer cells." (PMID 32937953, 2020). "Notably, cd4(Q5K,D9K) showed the highest cytotoxicity (IC50 1 μM) of all the analogs tested on the cancer cell line." (PMID 32153522, 2020). "In immunotherapy, by ensuring the transmission of signals from CD4+ T cells to CD8+ T cells and regulating the metabolic activities of T cells, the CTL response can be optimized, which may enhance anti-cancer immunity." (PMID 33183286, 2020). "The inflamed phenotype presented with infiltration of many immune cells and increased intensity of CD8+T cells, infiltration of CD4+T cells, B cells (CD20+), and histocytes (CD163+) in the cancer cell nest, determined by immunohistochemistry, when compared with non-inflamed immune-activated RVT." (PMID 33299121, 2020). "A CD4 Th1 response against the pool of UCP peptides was detected before any treatment in about 25% of blood samples from metastatic non-small cell lung (NSCLC), anal or renal cancer patients." (PMID 32630460, 2020). "We further found that pDC in TNBC was strongly positively correlated with the fraction of CD8+ T cells and CD4+ memory T cells, and the level of IFN-γ score as well as cytolytic activity score, which suggests an overall anti-cancer immune microenvironment and immune activity." (PMID 33198125, 2020). "Depletion of CD4+ and CD8+ T cells reduces anti-cancer efficacy of IL-12 expressing NV1042, which is similar to anti-cancer effects of non-IL12-expressing NV1023, indicating IL-12 expression plays an important role in enhancing oncolytic efficacy through immune modulation." (PMID 32050597, 2020). "This age-related increase of the CD4+/CD8+ T-cell ratio was not seen in our group of cancer patients." (PMID 32082401, 2020). "The CD4+ subset of T cells are the regulators of the adaptive immune response, whereas the CD8+ subset, also known as cytotoxic T cells (Tc cells) are involved in the defense mechanism against various intracellular pathogens as well as cancer cells." (PMID 32121269, 2020). "Nevertheless it has become evident that genetic ablation of TGF-β signaling pathway components in selected immune cell types (e.g., CD4+ and CD8+ T cells, NK cells, or dendritic cells) can re-activate the anti-tumor response in different cancer pre-clinical models." (PMID 31948072, 2020). "In addition, AUNIP expression was significantly related to the infiltration degree of CD4+ T cells, CD8+ T cells, neutrophils, macrophages, and DCs in 11, 12, 15, 14, and 15 cancer types, respectively." (PMID 33363020, 2020). "Similar to other CXCRs, CXCR6–CXCL16 could recruit immune cells (e.g., CD4+ and CD8+ T cells) to cancer sites to affect cancer progression, but the cell-specific functions of CXCR6 remain largely unclear." (PMID 33324682, 2020). "In addition to cytotoxic T cells, CD4+ T cells also infiltrate the tumors and are key in the response to cancer, by coordinating the activation and function of the CTL against cancer cells." (PMID 32326073, 2020). "Interestingly, preliminary results based on the evaluation of EuroFlow IMM TCD4 tube in patients with MBL, SM (two early cancer models), and CVID showed distinct patterns of alteration of CD4 T-cell subsets in blood." (PMID 32174910, 2020). "The relative potency of IL-12 to boost cancer immunity when delivered by TCR-engineered CD4+ or CD8+ has not yet been explored." (PMID 32708397, 2020).
cancer (continued). "Although the role of CD4+ CD25 +regulatory Tregs in maintaining immune homeostasis has studied been extensively, recent findings indicate that CD8 + Tregs potentially play an immunomodulatory role in cancer." (PMID 32547401, 2020). "We pose that provision of CD4+ T cell help, or the key signals that recapitulate help for CD8+ T cells will be crucial for the development of effective immunotherapeutic strategies in chronic infection and cancer." (PMID 33123174, 2020). "Then, the basic properties of ssCART-19 cells, including transduction efficiency, the CD4/CD8 ratio after transduction, proliferation, and cytotoxicity to the corresponding cancer cells were characterized and compared with the same features of regular CART-19 cells." (PMID 32523801, 2020). "PD-1 and CTLA4 were significantly correlated with CD8+ T cell but not CD4+ naïve T cell counts in most cancers." (PMID 33072070, 2020). "We hope that the current study serves as a springboard for future investigations of PD-1 signaling in antigen-specific primary CD4+ and CD8+ T cell subsets, which may help identify novel anti-cancer therapeutics." (PMID 33077516, 2020). "Previous studies have reported that the ratio of CD4+ T cells to CD8+ T cells plays a central role in the induction of efficient immune responses against diseases such as human immunodeficiency virus and some cancers." (PMID 32046726, 2020). "That calcium EP can upregulate IL-10 secretion from both CD4+ and CD8+ T cell cocultures in a dose dependent manner indicates that high dose calcium administration may inhibit anti-cancer immune responses as directed by exposed BMDMs47." (PMID 33244152, 2020). "WISP1 expression was significantly correlated with infiltrating levels of B cells in 7 types of cancer, CD8+ T cells in 8 types of cancer, CD4+ T cells in 9 types of cancer, macrophages in 17 types of cancer, neutrophils in 15 types of cancer, and dendritic cells in 16 types of cancer." (PMID 32523603, 2020). "Though the role of CD4+CD25+CD127lowTregs on the cancers has been reported, its clinical utility has not been fully elucidated." (PMID 32218692, 2020). "Similarly, both CD4+ and CD8+ Temra populations in cancer patients are found to be clonally expanded." (PMID 32272497, 2020). "However, a majority of studies use antibodies targeted to key surface markers to broadly identify major TIL subsets in cancer such as CD20 (B cells), CD3 (T cells), CD4 & CD8 (T cells) and FOXP3 (Regulatory T cells or Treg)." (PMID 33013886, 2020). "The bone marrow serves as a reservoir for memory CD4+ T cells and memory CD8+ T cells, where they seem to be attracted by bone-derived cytokines, such as IL-7, and, interestingly, CXCL12, similar to cancer cells." (PMID 32326073, 2020). "Thus, vaccine platforms that induce both CD4+ and CD8+ T cell responses would be highly desirable to enhance the therapeutic efficacy of a neoantigen-directed cancer vaccine." (PMID 33298945, 2020). "Comparison of gene expression changes identified in CD4+ and CD8+ Yap-cKO TILs with clinical data from TCGA showed significant correlation of gene signatures with T-cell infiltration across a variety of human cancers." (PMID 31929526, 2020). "As well, the BMI>35 cohort had a significantly (P = 0.014) lower proportion of natural killer (NK) cells (i.e., for CD56 bright cells and a trend for CD56 dim cells) and a trend towards higher Tregs (CD4+CD127low/-CD25+FoxP3+ cells), suggesting a potentially poorer ability to eradicate cancer cells." (PMID 32027700, 2020). "This is related to the observation that cancer cells usually express the major histocompatibility complex (MHC) class I molecules required for recognition by CD8+ T cells, but not MHC class II, which are required for antigen recognition by CD4+ T cells." (PMID 32708397, 2020).
cancer (continued). "Therefore, we believe that this platform be widely used for point-of-care diagnosis such as small molecules (sodium, potassium, chloride, glucose), cancer markers (B-type natriuretic peptide or BNP, troponin I), cells (CD4), and nucleic acids (DNA, RNA)." (PMID 30820698, 2019). "However, we did observe a significantly higher frequency of central memory phenotype amongst CD4 and CD8 T cells within cancer tissue relative to adjacent and normal lung tissue." (PMID 30857561, 2019). "Kaplan Meier analysis showed that patients with low pretransplant proportions of CD4+CD45RChigh or CD8+CD45RChigh T cells had a significantly lower survival without cancer as compared to patients with high proportions." (PMID 30925186, 2019). "Results obtained from the cancer patients showed that therapies did not modify the percentage of CD4 and CD8 lymphocytes in both groups at different time points." (PMID 30889935, 2019). "For example, the CCI was positively correlated with resting mast cell, naïve B cell, resting memory CD4 T cell, and CD8 cell in most cancers and negatively correlated with macrophage M1, resting dendritic cell, follicular helper cell, and regulatory T cell in most cancers." (PMID 30791227, 2019). "To date, similar results are obtained with one additional clinically approved anti-cancer mAb, anti-Her2 (Herceptin), as well as other non-therapeutic mAbs such as anti-CD4 (OKT4) (unpublished data)." (PMID 32047498, 2019). "Additionally, CTLA-4 levels are inversely related to total CD4+ T cell population and directly related to HIV viral load and cancer progression." (PMID 31113482, 2019). "We next investigated whether the characteristics of CD4+ T cells, CD8+ T cells, and Treg cells were altered in MEs depending on the cancer type." (PMID 31801611, 2019). "Priming of CD4+ helper T cells requires binding of the TCR to antigens presented on MHC class II (MHC II), which is normally expressed in immune cells, but it has been detected on some cancer cells." (PMID 31112530, 2019). "A clinical trial of the anti-PD-1 antibody pembrolizumab in patients with HIV on anti-retroviral therapy and advanced-stage cancer, reported that pembrolizumab did not impair CD4+ cell counts or viral suppression." (PMID 31847881, 2019). "However, mature CD4+CD8+ double positive T cells have been described in the peripheral blood and tissues in various settings, including in human cancers." (PMID 30984190, 2019). "Group A cancers had significantly higher numbers of infiltrating CD3+T-cells, CD4+T-cells, CD8+T-cells and CD20+B-cells compared to Groups B and C and Groups A and B cancers had significantly higher numbers of infiltrating CD163+ macrophages compared to Group C." (PMID 31431617, 2019). "In addition, aside from macrophages, almost all types of immune cells, including B cells, CD8+ T cells, CD4+ T cells, neutrophils, natural killer (NK) cells, and dendritic cells (DC), are found in the TME, and some participate in the development of cancers." (PMID 31998650, 2019). "The fraction of CD4 cells within the lymphocyte population was not different in cancer patients before RT compared to healthy controls." (PMID 31500214, 2019). "In this perspective, we approach these promising new technologies from an immunological angle, first by identifying the CD4+ and CD8+ T cell subtypes that are imperative for robust anti-cancer immunity and subsequently discussing the molecular cues needed to induce these cells types." (PMID 31130945, 2019). "While exposure to mf did not alter the ability of monocytes to induce T cell proliferation, exposure to MDA and the other two cancer cell lines (U87 and OVCAR) significantly diminished their ability to promote allogeneic and autologous CD4+, and allogeneic CD8+ T cell proliferation." (PMID 29668679, 2018). "This collaboration between CD4 T cells and macrophages was also essential for successful cancer immune surveillance in non-solid cancers, as myeloma and B-cell lymphoma." (PMID 29780381, 2018).
cancer (continued). "Moreover, CD4+ T cell-derived cytokines, such as IL-17, can promote the direct expression of VEGF in human cancer cells, and TAM and TAN-derived ECM remodeling enzymes, such as MMP9, can induce the release of pro-angiogenic factors that are trapped in the ECM." (PMID 30355585, 2018). "Analysis of T cell subpopulations revealed that as a group, PBMC from cancer patients presented a decrease in the percentages of both CD4+ and CD8+ naïve T cells, accompanied by an increase in the percentages of EM and Eff CD4+ and Eff CD8+ T cells compared to control samples." (PMID 30123214, 2018). "Noteworthy, intratumoral CD4+ T cells play a key role in this process, promoting the pro-metastatic TAM phenotype through IL-4 and IL-13 production, which further highlights the dual role of CD4+ T cells in the early dissemination of cancer cells." (PMID 30355585, 2018). "Intriguingly, this murine model is also characterized by enhanced CD4+CD25+CTLA4+ Tregs generation, suggesting that Notch/NF-κB crosstalk may modulate Treg behavior in cancer." (PMID 30364244, 2018). "Similarly, the stimulation of CD4+ helper and CD8+ cytotoxic T cells by immunotherapy has shown encouraging results in cancer therapy." (PMID 29662489, 2018). "In addition, we found that blockade of BTLA signaling increased IFN-γ production in both circulating CD4+ and CD8+ T cells isolated from HCC patients, which strengthens the emerging notion that BTLA can be used as a target of cancer immunotherapy." (PMID 30116751, 2018). "Men with incident virus-associated cancers had lower CD4 and WBC counts over a 6-year window prior to diagnosis compared to men without cancer (p = 0.001 and 0.03, respectively)." (PMID 30315476, 2018). "Collectively, these new LSPs contain 8 promiscuous CD4+ T-cell epitopes overlapping with 6 main described CD8+ T-cell epitopes restricted to HLA-A2, A3, A1, and A24 for which spontaneous CD8+ T-cell responses have been identified in numerous cancer patients." (PMID 30483475, 2018). "There is no consensus in literature on the CD4/CD8 ratio in relation to post-transplant cancer development." (PMID 29946375, 2018). "The distinct changes of BTLA and HVEM on circulating CD4+ and CD8+ T cells could be taken into consideration when targeting BTLA or HVEM in cancer immunotherapy." (PMID 30116751, 2018). "Given a sample from one of the 23 supported TCGA cancer types set in the config file, a user can perform TIMER analysis that will report the estimated abundance of B cells, CD4 T cells, CD8 T cells, neutrophils, macrophages, and dendritic cells within their samples." (PMID 29649993, 2018). "The CD4+ Th1 response, which overlaps with CTL differentiation in CD8+ T cells, is notably characterized by IFN-γ production and responses against virus-infected cells and cancers." (PMID 29891791, 2018). "Indeed, high density of CD4 and CD8 positive T cells in cancer stroma has been correlated with longer survival times in NSCLC patients." (PMID 28904817, 2017). "We observed that CD4+FoxP3+ Tregs in TILs expressed higher levels of Helios and the relative percentages of Tregs co-expressing FoxP3 and Helios within the TME was significantly higher than NT or peripheral blood of cancer patients." (PMID 28388539, 2017). "PD-L1 is expressed on the surface of activated CD4+ and CD8+ T cells and on cancer cells." (PMID 28542574, 2017). "Measures of effector memory status in CD4+ cells failed to segregate CD4+ subpopulations by cancer type." (PMID 28146145, 2017). "An in vitro cytotoxic assay using mesothelin-expressing K562 cells revealed that CD4+CD26high T cells have a similar, if not enhanced, capacity to kill cancer compared to CD8+ cells." (PMID 29213079, 2017). "Crytotanshinone (CPT) showed potential therapeutic value in animal breast model through enhancing cytotoxic CD4+ T cells by up-regulating JAK2 and STAT4 phosphorylation, suggesting that STAT4 may be play opposite function with STAT3 in human cancers." (PMID 28422733, 2017).